PHF1 (PHD finger protein 1)
Diseases named in the same sentence as PHF1 in open-access papers (continued):
Sharing a sentence is not in itself a finding about the gene and the disease.
cancer (5 papers, 2018 to 2024). A tumor composed of atypical neoplastic, often pleomorphic cells that invade other tissues. "Upregulation of PHF1 in diverse cancers underlines its role in tumorigenesis." (PMID 38813086, 2024). "Indeed, when looking at all cancer types, high PHF1 expression is associated with a better prognosis, while high PHF19 expression is typically linked to a worse outcome." (PMID 37107696, 2023). "PHF1 is predominantly downregulated in cancer, while PHF19 is largely upregulated, implicating a potentially opposing role of these two proteins." (PMID 37107696, 2023). "Public data suggest that PHF1 is typically downregulated in many cancer types, and its low expression is often associated with a poorer prognosis." (PMID 37107696, 2023). "Especially the recurrent frameshift at the amino acid R6 of PHF1 suggests that abolishing the function of PHF1 is advantageous for cancer progression, consistent with commonly observed reduced gene expression of PHF1." (PMID 37107696, 2023). "Further studies are warranted to purify and characterize the phytochemicals present in plant extracts and investigate the anti-cancer activity of PHF1 in detail using cell culture models." (PMID 29378653, 2018). "A time- and dose-dependent study using cancer cell lines is warranted to investigate how PHF1 elicits cytotoxicity to cells." (PMID 29378653, 2018). "In addition to the role of PHF1 itself, PHF1 is also commonly involved in gene rearrangements in some cancer types." (PMID 37107696, 2023). "Moreover, the anti-cancer activity of PHF1 should be investigated in detail." (PMID 29378653, 2018). "In oncogenesis, PHD finger proteins like PHF1, PHF5A, and PHF8 contribute to cancer progression by dysregulating chromatin." (PMID 38813086, 2024). "For instance, PHF1 engages with PRMT5–WDR77 and CRL4B complexes to promote cancer progression, while PHF5A’s interaction with the SF3b spliceosome and PAF1 impacts apoptotic pathways and cellular behavior across various cancers." (PMID 38813086, 2024). "In contrast to PHF1 and MTF2, PHF19 has primarily been described as an oncogene in multiple cancer types." (PMID 37107696, 2023). "In the following, we will address the known roles of PHF1, MTF2, and PHF19 in cancer and the possible mechanisms involved." (PMID 37107696, 2023). "One mechanism that regulates PHF1 expression levels in cancer involves the RNA-binding protein FTO, which stabilizes the PHF1 mRNA." (PMID 37107696, 2023).
infection (3 papers, 2016 to 2025). The state of being infected such as from the introduction of a foreign agent such as serum, vaccine, antigenic substance or organism. "Consistently, we observed that infection with lenti-siInppl1 abrogated Aβ-induced tau phosphorylation (PHF1, CP13) in primary cortical neurons." (PMID 27834631, 2016). "By the infection of 1N4R tau containing lentivirus particles, the expression levels of 4R tau and phosphorylated tau (AT8, PHF1) were increased in neurons." (PMID 40276591, 2025).
PHF1 also shares sentences with these, for which no sentence is quoted: lung adenocarcinoma (2 papers); alveolar soft part sarcoma (1); cavernoma (1); COVID-19 (1); delirium (1); diabetes (1); epithelioid hemangioendothelioma (1); Ewing sarcoma (1); ischemia (1); memory (1); motor neuron disease (1); myxoid liposarcoma (1); neurodegenerative disease (1); ovarian sex cord-stromal tumor (1); Pick disease (1); respiratory disorders (1).